PVR (PVR cell adhesion molecule)
Diseases named in the same sentence as PVR in open-access papers (continued):
Sharing a sentence is not in itself a finding about the gene and the disease.
cancer (continued). "ADM was found to exhibit a strong and consistent positive correlation with several immune checkpoint genes, including CD274 (PD-L1), CD276, TNFRSF18, TNFSF9, and PVR in the pan-cancer analysis, which contributed to the development of a suppressive immune microenvironment." (PMID 40529377, 2025). "However, it was noteworthy that among these immune-related genes, CD274, CD276, TNFRSF18, TNFSF9, and PVR displayed strong correlations with ADM expression across almost all cancer types." (PMID 40529377, 2025). "Importantly, the development of cancer in many cases is accompanied by the presence of soluble PVR/CD155 that can serve as a biomarker." (PMID 39335111, 2024). "Hedgehog signaling is often activated in cancer, and PVR is upregulated by the signaling." (PMID 39156900, 2024). "There are also many reports on ligands for PVRL2 and PVR in cancer." (PMID 39156900, 2024). "It has also been demonstrated that PVR expression correlates with poor prognosis in many cancers." (PMID 39156900, 2024). "Although it remains unclear whether increased production of sPVR represents a cause of cancer development, soluble ligand forms may act as a decoy protein, preventing the interaction of DNAM-1 with PVR-positive tumors." (PMID 37760586, 2023). "KIR2DL5+ immune cells infiltrated in various PVR+ human cancers." (PMID 36377656, 2022). "Their wide expression suggests that TIGIT interaction with PVR could hamper the anti-cancer immune surveillance." (PMID 36544779, 2022). "IHC staining showed that PVR protein was widely expressed in those cancers." (PMID 36377656, 2022). "KIR2DL5+ immune cells infiltrated in various types of PVR+ human cancers." (PMID 36377656, 2022). "Cancer immunotherapy targeting the TIGIT/PVR pathway is currently facing challenges." (PMID 36377656, 2022). "The overexpression of PVR has been reported in many cancers." (PMID 36552960, 2022). "However, PVR expression varied across cancers, reflecting differences in the collection methods for different data and hidden genetic mechanisms." (PMID 36552960, 2022). "Indeed, we observed KIR2DL5+ immune cells infiltrated in various human cancers that highly expressed PVR." (PMID 36377656, 2022). "The effect of PVR on the prognosis of cancer patients may be mediated by endogenous biological and immunological functions." (PMID 35625835, 2022). "Previous studies showed that blockade of TIGIT/PVR signaling could reverse T and NK cell dysfunction in various cancers." (PMID 34150627, 2021). "We firstly discovered that an FDA-approved anti-hypotensive drug azelnidipine could be repositioned for cancer immunotherapy by dual targeting SIRPα and PVR through docking-based virtual screening." (PMID 34068552, 2021). "Dual-target small molecule inhibitor (SMI) co-targeting the CD47/SIRPα and TIGIT/PVR may also exert exciting effects in the cancer immunotherapy." (PMID 34068552, 2021). "Antibodies targeting TIGIT/PVR pathway have achieved good effects in cancer treatment." (PMID 33557880, 2021). "Our results support a pro-apoptotic and anti-cancer role of the NF-kB p65 subunit in NB cells, via transient transfection, through enhanced NK-cell-mediated recognition and killing of NB cells following upregulation of Fas and PVR." (PMID 34503178, 2021). "Blockade of TIGIT/PVR is considered as a promising strategy in cancer immunotherapy." (PMID 33557880, 2021). "Therefore, the development of other types of drugs targeting TIGIT/PVR pathway is essential for cancer intervention and treatment." (PMID 33557880, 2021). "Our research provides a promising candidate for cancer immunotherapy based on TIGIT/PVR blockade." (PMID 32894141, 2020). "This is relevant for cancer therapy, as chemotherapy might induce the expression of PVR and therefore either improve immune response or increase immunosuppression." (PMID 32489646, 2020).
cancer (continued). "PVR is an integral membrane protein that binds poliovirus and is of interest because it is upregulated during the response to DNA damage, a process that occurs in viral infections and cancers." (PMID 32489646, 2020). "Our results broaden the knowledge that TIGIT could not only express on immune cells, but also on cancer cells, and this intrinsic expression may deliver inhibitory signals through the interaction with PVR on CD8+ T cells and NK cells." (PMID 30555485, 2018). "The blockade of TIGIT/PVR interaction is a promising approach in cancer immunotherapy." (PMID 30555485, 2018). "Finally, we checked for the effect of TAK-981 on (i) TIGIT (inhibitory receptor) and DNAM1 (activating receptor), which compete for binding to PVR and Nectin-2 on cancer cells, and (i) LFA1, which binds to ICAM-1 and stabilizes NK interaction with their target cells." (PMID 40661051, 2026). "Notably, TNFRSF18, LAG3, and PVR exhibit significant differences in 13 to 15 cancers." (PMID 40867324, 2025). "Moreover, we observed KIR2DL5+ immune cells infiltrated in various PVR+ human cancers." (PMID 36377656, 2022). "High expression of PVR(CD155 and CD112) could be associated with a poor survival in several cancer." (PMID 34631507, 2021). "Focusing on the co-stimulatory signals, we found that the PVR-TIGIT signaling axis, primarily received by GZMB+ CD8+ T cells and Tregs, is significantly upregulated in VPS25high cancer cells." (PMID 40149859, 2025). "The heatmap reveals significant differences in the signaling of ICAM, ALCAM, PVR, IL1, and CD137 emitted by VPS25high and VPS25low cancer cells." (PMID 40149859, 2025). "We demonstrate that cancer-derived blebbisomes contain a plethora of inhibitory immune checkpoint proteins, including PD-L1, PD-L2, B7-H3, VISTA, PVR and HLA-E." (PMID 39984653, 2025). "The engagement of TIGIT with its binding partners, poliovirus receptor (PVR) (CD155), nectin-2 (CD112), and nectin-4 (PVRL4)—plays a pivotal role in modulating immune reactions and the evolution of cancer." (PMID 40777027, 2025). "Recently, the IC axis involving the poliovirus receptor (PVR, CD155), poliovirus receptor-like 2 (PVRL2, CD112), and T cell immunoreceptor with Ig and ITIM domains (TIGIT) has emerged as a promising target for cancer immunotherapy." (PMID 40317320, 2025). "We find that cancer cells release blebbisomes containing an abundance of immune evasion and inhibitory immune checkpoint proteins, including PD-L1, PD-L2, B7-H3, VISTA, PVR, Nectin-2, HLA-E, CD73 and CD47." (PMID 39984653, 2025). "The identification of the poliovirus receptor (PVR, CD155) as a ligand for KIR2DL5 in 2019 has opened new avenues of research in cancer immunotherapy, particularly in the context of BC." (PMID 40977889, 2025). "Our analysis revealed that elevated PLEK2 expression was significantly associated with increased expression of several key immune checkpoint molecules, such as CD276 (B7-H3), CD274 (PD-L1), LGALS9, PVR (CD155), and FAS across a wide spectrum of cancers." (PMID 39546161, 2024). "Our analysis indicated a positive correlation between B3GNT5 and immune activation markers, including CD276, PVR, NT5E, STING1, and TNF-SF18, as well as immunosuppressive genes TGF-ΒR1, IL-10PR, KDR, CD274, PDCD1LG2, IL-10, and IDO1 in the pan-cancer cohort." (PMID 39671359, 2024). "CD155, also recognized as the poliovirus receptor (PVR), is a transmembrane glycoprotein frequently characterized by elevated expression in several cancer types, including TNBC." (PMID 38216949, 2024). "In vivo, PVR binds to TIGIT and inactivates CD8+ T cells, and targeting PVR-TIGIT promotes CD8+ T cell responses and improves survival in cancer-bearing mice." (PMID 39156900, 2024). "CD155, also known as the poliovirus receptor (PVR), is a crucial molecule in the development and progression of cancer, as its overexpression favors immune evasion and resistance to immunotherapy." (PMID 39596207, 2024).
cancer (continued). "TIGIT competes with inhibitory receptors KIR2DL5A and PVRIG and activating receptor CD226 (DNAM-1) to bind ligands CD155 (PVR) and CD112 (Nectin-2 or PVRL2) which are commonly expressed on cancer cells and antigen-presenting cells (APCs)." (PMID 37345049, 2023). "Correspondingly, poliovirus receptor (PVR, CD155), one of the main ligands of TIGIT, is mainly expressed in various human malignant tumors and myeloid cells." (PMID 35433470, 2022). "Moreover, PVR may regulate cancer immunity by regulating the level of immune cell infiltration." (PMID 36552960, 2022). "CD155 (also named poliovirus receptor or PVR) is an immune checkpoint protein that belongs to the Nectin-like family and is expressed on the surface of cancer and immune cells." (PMID 36428703, 2022). "Since we demonstrated the immune inhibitory function of the KIR2DL5/PVR pathway and its presence within the TME of various human cancers, we wanted to develop a new cancer immunotherapy by targeting this pathway." (PMID 36377656, 2022). "PD-L1 and PVR, the respective ligands for PD-1 and TIGIT, are upregulated in cancer and chronic viral infection." (PMID 33767694, 2021). "DNAM-1 recognizes two ligands, CD155 (poliovirus receptor, PVR) and CD112 (Nectin-2), that are widely expressed by cancer cells." (PMID 34712615, 2021). "DNAM-1 recognizes two ligands belonging to the Nectin family, CD155 (PVR) and CD112 (Nectin-2), which are widely expressed on various tissues and cancers." (PMID 35008589, 2021). "TIGIT binds to three ligands, namely CD155 (PVR), CD112 (Nectin-2), and CD113 (Nectin-3), that are expressed on APCs and cancer cells." (PMID 34948104, 2021). "Collectively, consistent with the previous literature, our results revealed the over-expression of CD47 and PVR in tumors, suggesting the promising role of CD47 and PVR in cancer immunotherapy." (PMID 34068552, 2021). "DNAM-1 binds to CD112 (also known as nectin 2) and CD155 (also known as the poliovirus receptor, PVR), which is improperly expressed in cancer cells." (PMID 34439285, 2021). "Therefore, the development of TIGIT/PVR inhibitors may have potentials in cancer immunotherapy." (PMID 33557880, 2021). "Our research provides a promising candidate for cancer immunotherapy, bridging the innate and adaptive immunity by a CD47/SIRPα and TIGIT/PVR blockade." (PMID 34068552, 2021). "TIGIT and CD226 interact with the two nectin-family members poliovirus receptor (PVR) (CD155/Necl-5/Tage4) and poliovirus receptor-related 2 PVRL2 (CD112), which are widely expressed on different cell types and on cancer cells." (PMID 32155826, 2020). "In other cancer types, such as KIRP, MESO, and CHOL, PVR expression also seems to be related to a putative intergenic enhancer in an intron of IGSF23." (PMID 33343635, 2020). "PVR is also broadly expressed in tumors, suggesting that the TIGIT-PVR axis provides a major immune escape mechanism for cancer cells." (PMID 31575023, 2019). "TIGIT and CD226 are paired receptors that compete for shared ligands CD155 (PVR) and CD112 (Nectin-2) expressed by cancer and antigen-presenting cells." (PMID 30400822, 2018). "PVR and PD-L1, as the corresponding ligands of TIGIT and PD-1, respectively, were also expressed in these murine cancer cell lines." (PMID 30555485, 2018). "Finally, we confirmed that the expression levels of the top immunosuppressive genes, EBAG9, PVR, TGFB1, B7-H3, TNFRSF14, and PD-L1, were significantly higher in the high-p62 group than in the low-p62 group in most cancers." (PMID 41291343, 2025). "Looking at the cancer cells, we observed a reduction in the number of LDHC-silenced cancer cells expressing PD-L1, PD-L2 and CD80, and decrease in the cell surface expression of PD-L2, Gal-9, PVR, HLA-DR and VISTA." (PMID 40108668, 2025). "We found that cancer-cell-derived blebbisomes express not only PD-L1 but also a plethora of other inhibitory ligands, including PD-L2, B7-H3 (CD276), VISTA (B7-H5), HLA-E, PVR (CD155) and Nectin-2 (CD112)." (PMID 39984653, 2025).
cancer (continued). "Consistent with a Carcinoma 3–T cell niche in SCC, robust signaling to Tregs was facilitated through multiple ligand–receptor interactions, encompassing TNFSF9‐TNFRSF9 and CXCL16‐CXCR6, as well as PTN‐SDC4, PVR‐CD96, and PVR‐TIGIT." (PMID 40776410, 2025). "Furthermore, the expression of CD276, MICB, PVR, TGFB1, and TGFBR1 displayed high correlations with TUBA1B expression in most cancers." (PMID 38589634, 2024). "In addition, SHP-77, a TIGIT ligand (CD155, PVR)-positive cancer cell line, was added to the culture." (PMID 38724599, 2024). "Interactions of several ligand-receptor pairs between cancer cells and immune cells (CD274:PDCD1, FAM3C:PDCD1, PVR:TIGIT) are predicted to be enhanced in NRF2 signature high samples which could be potential targets to inhibit to remodel the TME." (PMID 38241355, 2024). "Also, in most of the cancers, there was a significant correlation between UBE2C gene expression and C10orf54, CXCL12, IL6R, MICB, PVR, THEM173, and TNFSF13." (PMID 38577722, 2024). "We found that high expression of PVR and NECTIN2 predicts poor prognosis in a variety of cancers." (PMID 39120585, 2024). "Notably, two specific immunostimulators, PVR and MICB, demonstrated significant and positive correlations with WDHD1 across multiple types of cancer." (PMID 37759234, 2023). "The TIGIT/PVR and the TIM-3 pathways have recently been shown to be involved in the macrophage polarization, suppression of pro-inflammatory cytokine production, and cancer cell growth in several mouse models." (PMID 37876933, 2023). "PVR also has a high affinity to TIGHT, which is a promising new target for cancer immunotherapy." (PMID 35646872, 2022). "Our results revealed that in GBM cancer cells, expression of CD274 (PD-L1), PDCD1LG2 (PD-L2), LGALS9 (Galectin-9), and PVR (CD155) were positively correlated with the expression of multiple m6A regulators, especially YTHDF2, YTHDF3, LRPPRC, METTL3, RBM15B, FTO, and ALKBH5." (PMID 35558067, 2022). "Notably, in GBM cancer cells, CD274 (PD-L1), PDCD1LG2 (PD-L2), LGALS9 (Galectin-9), and PVR (CD155) were correlated with m6A regulators." (PMID 35558067, 2022). "Our findings suggest that PVR might be a potential prognostic marker for HCC and can be used to determine the infiltration of immune cells in cancer tissues." (PMID 36552960, 2022). "In cancer, commonly upregulated ligands include MICA and MICB (MHC-class I polypeptide-related sequence A and B), the UL16-binding proteins (ULBPs) and the adhesion molecules PVR (poliovirus receptor, also known as CD155) and Nectin-2." (PMID 35242135, 2022). "Although PVR expression is low or absent in most healthy tissues, in several human cancers, an upregulation of both membrane and soluble forms was observed and correlated with poor prognosis." (PMID 36011052, 2022). "Subsequently, PVR was identified as the ligand of co-stimulatory molecule CD226 and co-inhibitory immune checkpoint TIGIT, indicating more attention should be paid to its importance in cancer immunity." (PMID 32894141, 2020). "As shown in our study, the blocking of PVR and PVRL2 combined with other promising immunological approaches like BiTE® antibody construct therapies might be beneficial for cancer treatment." (PMID 29855615, 2018). "Here, we analyzed the possibility that treatment of MM cells with different NO-donors could regulate the expression of the NK cell activating ligand PVR/CD155 and, in turn, modify NK cell recognition and cytotoxicity against these cancer cells." (PMID 25609078, 2015). "Additionally, interactions between FOXP3high/+ Tregs and cancer cells may be involved in Treg mobilization (CXCR6/CXCL16) and activity (TIGIT/PVR)." (PMID 40164596, 2025). "In addition, there are reports on the expression of PVR and PVRL2 in many other cancers." (PMID 39156900, 2024). "However, the axis PVR/TIGIT signaling between NK cells and cancer cells is bidirectional." (PMID 39511139, 2024).
cancer (continued). "Depending on the type of cancer, either PVRL2 or PVR may be expressed predominantly." (PMID 39156900, 2024). "While receptor heterogeneity holds true for PVR, the interplay between the receptors i.e. TIGIT blocking CD226 mediated co-stimulation, allows us to envision developing PVR as a dual functioning therapeutic with potential utilization in both cancer and autoimmune therapy." (PMID 36944702, 2023). "In addition, CCNA2 could positively regulate TAP1, TAP2, CD276, MICB, PVR, and ULBP1 in almost all the cancer types." (PMID 35401923, 2022). "Indeed, these cancer cells can express high levels of NKG2D ligands MHC class I chain-related protein A and B (MICA/B) and different UL16 binding proteins (ULBPs), and the DNAM-1 ligands Poliovirus Receptor (PVR) and Nectin-2." (PMID 33499314, 2021). "Moreover, soluble PVR levels have been seen to be upregulated in sera of cancer patients, but its role is not yet clear." (PMID 34209558, 2021). "However, in the case of cancer, such negative signaling is of interest, and the idea of blocking PVR becomes attractive." (PMID 32489646, 2020). "Moreover, in AML patients, high expression levels of PVR and CD112 correlated with poor prognosis, thus suggesting that CD155 and CD112 or their cognate receptors may be targeted in cancer immune checkpoint antibody therapy." (PMID 30841639, 2019). "The analysis of 46 immunostimulatory genes in pan-cancer showed that HSP90B1 expression was positively correlated with CD40, CD270, PVR, MICB, ULBP1, TNFSF4, while exhibiting a negative correlation with CD48 and CD40LG in most cancers." (PMID 38243263, 2024). "In terms of immune-activated genes, AURKA exhibited positive correlations with MICB, PVR, CD276, and ULBP1 and negative correlations with C10orf54 in most cancers." (PMID 37965456, 2023). "Therefore, this represents the first analysis of soluble PVR levels in patients with MM, as well as those with MGUS and without cancer." (PMID 35625835, 2022). "Because PVR and TIGIT proteins can be found in soluble forms, we quantified soluble PVR protein levels in bone marrow plasma from patients with MM, MGUS, and patients without cancer." (PMID 35625835, 2022).